HGF (hepatocyte growth factor)
Diseases named in the same sentence as HGF in open-access papers (continued):
Sharing a sentence is not in itself a finding about the gene and the disease.
tumor (continued). "HGF/SF mRNA was expressed in two of the examined tumours, and only one of these also expressed the c-met proto-oncogene." (PMID 7678980, 1993). "Furthermore, a cluster of cytokines (LIF, SDF-1, HGF, SCGFb) was identified as potentially involved in the regulation of PD-L1 expression by tumor cells." (PMID 41597220, 2026). "However, in the long term, the same niche created by CAFs provides the tumor with signals (HGF, bFGF) and promotes invasion and resistance." (PMID 41597220, 2026). "Consistent with the lack of the baseline and early response differences between the NSGhHGF and NSG xenografts in tumor growth and spatial distributions of cell proliferation, transcriptional analyses revealed the emergence of the HGF-dependent differences only after six weeks of treatment." (PMID 40313737, 2025). "This modification drastically alters the spatial structure of the extracellular section, enhancing its interaction with hyaluronic acid, metalloproteases, VEGF (vascular endothelial growth factor), and HGF (hepatocyte growth factor), which promotes the invasiveness and survival of tumor cells." (PMID 40649828, 2025). "Tumor cells that have undergone EMT express high levels of the hepatocyte growth factor (HGF) receptor (cellular-mesenchymal epithelial transition factor(c-Met)) and tend to accumulate near blood vessels, where they can interact with the vessel wall through extended membrane structures." (PMID 40995371, 2025). "Interestingly, HGF also directly affects immune cells, promoting the migration of immunosuppressive neutrophils to tumor sites and lymph nodes and inducing immunosuppressive dendritic cells, thereby dampening antitumor immune responses." (PMID 40867310, 2025). "Moreover, hepatocyte growth factor (HGF) is reported to collaborate with MMPs to further promote tumor progression." (PMID 39811803, 2025). "Signaling pathway activation and tumor cell survival: hepatocyte growth factor (HGF) secreted by CAFs activates the c-Met receptor and restores PI3K/Akt and MAPK/ERK signaling, leading to epidermal growth factor (EGFR)-tyrosine kinase inhibitor (TKI) resistance." (PMID 41346633, 2025). "For instance, we found elevated levels of tumor‐promoting HGF under D‐CC conditions." (PMID 40411295, 2025). "Therefore, comprehending the mechanisms that trigger the secretion of HGF in CAFs is crucial within the tumor microenvironment of CCA." (PMID 41048570, 2025). "Also, supportive information in the literature shows that signaling from MET, the receptor for hepatocyte growth factor, promotes pancreatic tumorigenesis and poor patient prognosis by enhancing tumor cell growth, survival, and motility." (PMID 40728965, 2025). "HGF binds to c‐MET receptors on tumor cells, stimulating tumor invasion and growth." (PMID 39801758, 2025). "Tumor-associated fibroblasts (CAFs) produce dense extracellular matrix (ECM) components such as collagen, fibronectin, and hyaluronic acid, while secreting pro-survival factors like hepatocyte growth factor (HGF)." (PMID 41247642, 2025). "Cancer cell motility can be elicited through biochemical cues emanating from the microenvironment, involving growth factors, such as TGF-β, fibroblast growth factors (FGF), and hepatocyte growth factor (HGF), and cytokine release, which permit cancer cells to break away from the primary tumor." (PMID 40643464, 2025). "The HGF/MET pathway has been identified as a critical role in tumor-stroma interactions." (PMID 39926258, 2025). "However, future studies should focus on the mechanisms by which DDR1 activation accelerates and the HGF–MET axis decelerates HCC tumor growth." (PMID 40248197, 2025). "Furthermore, correlations with HGF suggest that SIGLEC12 is involved in angiogenesis and tumor progression, as HGF promotes motility and invasion." (PMID 41303731, 2025).
tumor (continued). "In addition to ROS toxicity, TANs also induce tumor cell death by promoting the expression of nitric oxide synthase (iNOS) and the release of nitric oxide (NO) via hepatocyte growth factor (HGF)." (PMID 40160822, 2025). "Specifically, the activation of alternative angiogenic pathways—such as those involving angiopoietin-2 (Ang-2), hepatocyte growth factor (HGF/c-Met), and interleukin-8 (IL-8) —has been shown to restore neovascularization and tumor perfusion independently of VEGF/FGF signaling." (PMID 40362400, 2025). "Agents targeting the HGF/c-MET axis have shown clinical efficacy across multiple tumor types." (PMID 40520181, 2025). "However, HGF’s role is context-dependent: while beneficial in ischemia, HGF exacerbates tumor angiogenesis and atherosclerotic plaque vulnerability by upregulating matrix metalloproteinases (MMPs) and promoting intraplaque neovascularization." (PMID 41000109, 2025). "In addition, IL-6 autocrine increases the motogenic activity of tumor cells by binding to the receptor for IL-6 on the surface of tumor cells and increases the secretion of HGF, which promotes metastasis." (PMID 41007818, 2025). "This suggests that HGF expression in the tumor microenvironment is important for tumor growth." (PMID 39980226, 2025). "Tumor cells may bypass VEGFR inhibition by upregulating compensatory pro-angiogenic pathways such as the FGF/FGFR axis or hepatocyte growth factor (HGF)/c-MET signaling." (PMID 40284020, 2025). "Moreover, EGCG inhibits hepatocyte growth factor (HGF), which is involved in tumor migration and invasion." (PMID 39942757, 2025). "We unveil a spatially organized metabolic niche driven by stromal-tumor HGF-MET-MYC signaling." (PMID 41234356, 2025). "Additionally, preclinical studies have demonstrated that inhibition of the HGF/MET pathway suppresses tumour growth in multiple cancer models and, in some cases, overcomes resistance to other anticancer agents." (PMID 40599602, 2025). "This suggests that FGFR1-driven MIBC are characterized by HGF-rich tumor microenvironments, which may promote the expansion of MET-amplified subpopulations within heterogeneous tumors during erdafitinib treatment." (PMID 41315241, 2025). "Taken together, our spatial analyses support the notion that stroma-mediated resistance contributes to both incomplete tumor responses and tumor growth relapse, and indicate that, in vivo, stroma-mediated resistance cannot be reduced to the effects of the HGF-cMET axis alone." (PMID 40313737, 2025). "The aberrant activation of the HGF signaling pathway may drive the malignant transformation of Epithelial cells and tumor progression in the CS2 subtype, enhancing their invasive and metastatic capabilities." (PMID 40170854, 2025). "Besides, hepatocyte growth factor (HGF) secreted from iCAF promotes tumor growth by activating its receptor, Met on cancer cell." (PMID 40025612, 2025). "Moreover, IL-6 promotes angiogenesis, enhances cancer cell motility through hepatocyte growth factor (HGF) signaling, and impairs anti-tumor immunity by generating dysfunctional natural killer (NK) cells." (PMID 41007818, 2025). "Among these, hepatocyte growth factor (HGF) plays a prominent role by promoting tumor invasion through the disruption of the cell–cell adhesion complex, cell adhesion to the ECM, cell motility, and the production of matrix-degrading enzymes, such as MMPs and uPA." (PMID 40723336, 2025). "Additionally, exosomes acting as nanoparticles impede tumor advancement and angiogenesis in GC by transporting hepatocyte growth factor (HGF) siRNA." (PMID 40771798, 2025). "Additionally, neutrophils secrete cytokines including TGF-β, VEGF, OSM, IL-10, and HGF, which directly promote tumor angiogenesis and tumor progression." (PMID 40761249, 2025). "Moreover, G6PD promotes the production of hepatocyte growth factor (HGF) from tumor mesenchymal stem cells, which regulate tumor microenvironment surrounding cancer cells, via NF-kB activation." (PMID 41374996, 2025).
tumor (continued). "Due to the critical role of HGF/c-Met axis in angiogenesis and anti-tumor drug resistance in pathophysiological processes, this pathway has gradually become an attractive target for anti-tumor angiogenesis therapy." (PMID 40251641, 2025). "CAF markers such as α-SMA, HGF, and podoplanin in tumor tissues could predict EGFR-TKI resistance.Targeting CAF-derived factors such as HGF or using antifibrotic agents may counteract TKI resistance." (PMID 40002883, 2025). "Notably, in transgenic mouse models, blockade of the HGF–MET interaction significantly reduced tumour incidence and growth rate." (PMID 40599602, 2025). "Since HGF expression by the tumor itself or by its microenvironment may be required for full activation of MET variants having an N‐lobe mutation in HPRCC, HGF expression could be a valuable biomarker in this cancer." (PMID 39980226, 2025). "The HGF/c-Met axis plays a pivotal role in the intricate interplay between tumor and stromal cells." (PMID 39891818, 2025). "Of particular importance, as a candidate mediator of TKI resistance, the increased expression of HGF can lead to activation and amplification of the c-MET receptor in cancer cells and tumor-associated stroma, which is closely related to the acquired resistance to EGFR-TKIs." (PMID 40136462, 2025). "For instance, myofibroblastic CAFs (myCAFs) can secrete factors such as HA that promote tumor growth, while inflammatory CAFs (iCAFs) may release hepatocyte growth factor (HGF) that supports tumor progression." (PMID 39849659, 2025). "In addition, cancer‐associated fibroblasts (CAFs) produce HGF, VEGF, TGF‐β, IL6, CXCL1, CXCL12, and PD‐L2, promoting tumor growth and antagonizing antitumor immune responses by recruiting suppressive immune cells." (PMID 39170944, 2024). "The ability of E-cadherin-positive 4T1 cells to dissociate from tumor spheroids is reminiscent of the mechanical disruption of cell-cell junctions upon treatment of Madin–Darby canine kidney epithelial (MDCK) cells with hepatocyte growth factor (HGF)." (PMID 39104192, 2024). "The paracrine factors secreted by CAF involve, among others, vascular endothelial growth factors (VEGFs), PDGFs, hepatocyte growth factor (HGF), and other chemokines and cytokines that may be responsible for tumor vascularization." (PMID 38966131, 2024). "Thus, these aberrant fusions of the MET gene act as a “driver” for the activation of the MET protein and downstream signaling pathways, endowing tumor cells with HGF-independent self-activation ability." (PMID 38195556, 2024). "The acidic environment caused by LA accumulation promotes tumor progression and metastasis by EMT, since LA could activate the GF-β/Smad、Wnt/β-catenin、IL-6/STAT3 and HGF/MET pathway inducing EMT." (PMID 38689341, 2024). "On the other hand, findings suggest that high c-MET activity, reflected in elevated HGF levels, may contribute to an immunosuppressive tumor microenvironment that hampers the efficacy of PD-1/PD-L1 blockade." (PMID 39664377, 2024). "However, the precise role of the HGF/c-MET signaling pathway within the tumor immune microenvironment remains incompletely understood." (PMID 39201787, 2024). "Additionally, the increase in cytokines such as IL-6 and HGF emphasizes their role in surgery-induced tumor growth and metastasis and the role of other cytokines like MCP-2 in immunosuppression." (PMID 39451257, 2024). "Additionally, neutrophils and macrophages in the TME also contribute to HGF production, further supporting tumor growth through MET activation." (PMID 39598385, 2024). "Moreover, the secretion of HGF by senescent astrocytes drives tumor invasion, therapeutic resistance, and recurrence." (PMID 38342629, 2024). "A recent study found that M2 macrophages also secrete HGF to maintain tumor growth and metastasis." (PMID 39201787, 2024).
tumor (continued). "The infiltration of TAMs and immune cells thus represents a double-sided sword and on the one hand is associated with an effective response to immune checkpoint inhibitors, but on the other hand can support the growth of MET-expressing tumor cells via secreted factors such as HGF." (PMID 38386085, 2024). "CDK2 became less active while HGF became more active indicating a switch to a MES-like tumor." (PMID 38766170, 2024). "Additionally, studies have reported that SLC16A1, besides its function as a proton transporter, can also induce epithelial-mesenchymal transition in tumor cells by activating the HGF/C-MET pathway, thereby promoting tumor invasion and metastasis." (PMID 38911368, 2024). "Thirdly, it needs to be further investigated whether HGF and TGF-β1 tissue expression is associated with induction by chemotherapy or tumor burden." (PMID 38392578, 2024). "Furthermore, antineoplastic neutrophils mediate the release of IL-1 and hepatocyte growth factor (HGF) to exert antibacterial activity and increase the production of iNOS to kill tumor cells, respectively." (PMID 38590651, 2024). "VEGF plays a crucial role in angiogenesis, with its upregulation in tumor cells under hypoxic conditions leading to synergistic effects with HGF in promoting endothelial cell proliferation, migration, and vascular structure formation, thereby facilitating tumor angiogenesis." (PMID 39201787, 2024). "Evidence has demonstrated TANs not only promote invasion and angiogenesis by producing MMP-9, vascular endothelial growth factor (VEGF), and hepatocyte growth factor (HGF) but also promote distant migration and dissemination through ensnaring tumor cells via neutrophil extracellular traps (NETs)." (PMID 38348027, 2024). "Recently, HGF has been shown to be present in the tumor microenvironment and plays a critical role in the maintenance of the stemness properties of CSCs, suggesting that molecules that inhibit the HGF pathway may be potential anti-CSC reagents." (PMID 38794215, 2024). "Reactive microglia and immune cell released HGF might hence be responsible for the activation of growth factor/survival signaling in adjacent tumor cells." (PMID 38386085, 2024). "In vivo studies showed that HGF suppressed tumor growth with a long immune memory response." (PMID 37984863, 2024). "Moreover, the interaction between c‐Met and HGF can stimulate tumor cell mitosis, motility, angiogenesis, migration, and invasion." (PMID 39092291, 2024). "Neutrophils in the primary tumor microenvironment are closely associated with the local inflammatory response and can promote tumor invasion, metastasis, and angiogenesis through the release of hepatocyte growth factor, neutrophil elastase, and matrix metalloproteins." (PMID 38112787, 2024). "Specifically, HGF has the ability to attract neutrophils for anti-tumor activities, while MET serves as a tumor-associated antigen (TAA) in facilitating immune-mediated tumor destruction." (PMID 39201787, 2024). "In addition, HGF plays an important role in promoting hepatocyte regeneration while participating in normal tissue repair after injury, cell motility, tumor formation, invasion and metastasis, differentiation, and tumor vascularization." (PMID 39456754, 2024). "Further exploration of the HGF/Met signaling pathway’s involvement in this interplay is crucial for elucidating the intricate mechanisms of tumor biology and laying the groundwork for novel therapeutic approaches to enhance the effectiveness of immunotherapy and the outcomes of cancer patients." (PMID 39201787, 2024). "Activation of c-MET on the surface of neutrophils by HGF leads to chemotactic attraction to tumors and the release of nitric oxide to kill tumor cells, whereas conditional deletion of the MET gene in neutrophils promotes tumor growth and spread to other organs." (PMID 39201787, 2024). "HGF/c-Met signaling axis plays a role in tumor progression and metastasis." (PMID 38935609, 2024).
tumor (continued). "Furthermore, we suggest interferon-induced expression of HGF in tumor cells triggered by interferon-gamma provided by stromal cells mediates autocrine activation of MET-signaling in tumor cells." (PMID 38386085, 2024). "TAMs could contribute to tumor development by inducing the expression of hepatocyte growth factor (HGF)." (PMID 39170620, 2024). "Moreover, myofibroblast-secreted HGF can restore differentiated tumor cells from the cancer stem cells." (PMID 38817451, 2024). "Several studies confirmed that the integrity of HGF and its receptor (c-Met) could regulate cell proliferation and motility, promoting tumor progression." (PMID 38817451, 2024). "Furthermore, secretion of growth factors such as TGF-β or HGF by CAFs drives epithelial-to-mesenchymal-transition of tumor cells, while stromal-derived factor 1 increases tumor growth and neoangiogenesis [19,]." (PMID 38833784, 2024). "However, we also show that human HGF (hHGF) is required, as demonstrated in vivo using a humanised HGF knock‐in strain of mice and further detected in tumour cells of METex14 NSCLC patient samples." (PMID 36799689, 2023). "In addition, we were able to identify different populations of tumor capsule overexpressing cancer-associated fibroblasts (CAFs) markers such as FAP, VIM, and ACTA2 as well as hepatic stellate cells markers (HGF, LRAT, RGS5)." (PMID 37932266, 2023). "In addition, HGF‐producing fibroblasts promoted entrectinib resistance in vitro (culture model) and in vivo (subcutaneous tumor model)." (PMID 36416133, 2023). "In vivo, HGF is secreted from the tumor stroma and organs such as the liver." (PMID 37381723, 2023). "However, as HGF was found required for METex14‐dependent spheroid survival and tumour growth, these results indicate that some changes already occur with exon 14 splicing in the absence of HGF although they are not sufficient to drive MET oncogenicity." (PMID 36799689, 2023). "Furthermore, we detected the expression of HGF using tumor tissue and paired plasma samples from a validation cohort of 71 SCLC patients at our institute." (PMID 37828456, 2023). "The findings of the present study suggest that HGF, which can exist in the tumor microenvironment, may be involved in the emergence of DTPs against entrectinib treatment." (PMID 36416133, 2023). "The absence of a connection between HGF level and DIC severity across the entire cancer cohort may be a result of the complex interplay between blood clotting, tumor tissue, and HGF." (PMID 37504277, 2023). "Our findings suggest that growth factors in the tumor microenvironment, such as HGF, may induce resistance to entrectinib in tumors with NTRK1 or ROS1 rearrangements." (PMID 36416133, 2023). "HGF has been discovered to regulate the activity of various immune cell types, including B cells, T cells, and natural killer cells, which are important components of the anti-tumor immune response." (PMID 38022627, 2023). "For example, after transfection of HEK 293T cells with synthetic siR that targets the expression of hepatocyte growth factor (HGF), there was an increased secretion of HGF-harbouring EVs with an inhibitory effect on tumour growth and angiogenesis in vitro and in vivo." (PMID 37189850, 2023). "While it is unclear whether HGF activates MET in a paracrine or autocrine way, elevated tumor-stroma interactions were associated with unfavorable responses to EGFR TKI in clinical practice." (PMID 36647832, 2023). "In vitro, interference of the HGF-cMET pathway inhibited tumour growth and migration." (PMID 35953652, 2023).